CLDN7 (claudin 7)
Diseases named in the same sentence as CLDN7 in open-access papers (continued):
Sharing a sentence is not in itself a finding about the gene and the disease.
gastric cancer (22 papers, 2011 to 2025). A primary or metastatic malignant neoplasm involving the stomach. "This cluster displayed a signature of proliferating and activated cells, as evidenced by the prominent expression of genes such as Claudin-7 (CLDN7), which are associated with gastric cancer cell proliferation and invasion." (PMID 38067255, 2023). "Downregulation of CLDN7 was determined in breast cancer and head and neck cancer, whereas elevated levels of this protein were indicated in stomach cancer." (PMID 38201579, 2023). "Claudin family proteins have been declared to be expressed differently in diverse tumor tissues and CLDN7 was particularly relevant to gastric cancer, colon cancer, and pancreatic cancer." (PMID 31998788, 2020). "Claudin-3 and claudin-7 were expressed in 25.4% and 29.9% of the gastric cancer tissues, respectively." (PMID 31861759, 2019). "Claudin-7 expression correlated with shorter overall survival in gastric cancer patients, while the overall survival was increased in patients with claudin-18 expression." (PMID 31861759, 2019). "Analysis of EC96 cells derived from AGS gastric cancer cells showed that E-cadherin re-expression enhanced cell migration speed and straight movement through regulation of tight junction (TJ) protein, ZO-1, and claudin-7 expression." (PMID 34064908, 2021). "The influence of claudin-3, claudin-7, and claudin-18 in gastric cancer patients were also studied." (PMID 31861759, 2019). "Classes toSTAD and toTHCA can also be separated for gastric cancer with proteins characteristic to class toStad being Cyclin_B1, Caspase-7_cleavedD198, and Claudin-7 whereas toTHCA cases have significantly increased expression/phosphorylation of NF-kB-p65_pS536 and Caveolin-1." (PMID 30442178, 2018). "Nevertheless, in some studies high claudin-7 expression was significantly associated with a poorer prognosis of the patients with gastric cancer which did not correspond with our study." (PMID 27398181, 2016). "However, CLDN7 is expressed in various normal tissues with less specificity, and could be inadequate for gastric cancer detection." (PMID 27580354, 2016). "It has been reported that IRF2 inhibits cell proliferation by inducing CLDN7 upregulation in oral squamous cell carcinoma, and inhibits cancer proliferation by promoting AMER-1 transcription in human gastric cancer." (PMID 36341357, 2022). "Only three, CLDN7, CLDN1 and DPT, of these genes are significantly differentiated in all grades or stages of gastric cancer." (PMID 21445269, 2011). "Using the top eight upregulated genes (SLPI, PLA2G2A, CXCL1, CCL20, REG1A, CLDN7, PI3, LGALS3) as a representative gene set for the high metabolic subcluster, we calculated the GSVA score of this gene set for each patient in the TCGA gastric cancer cohort." (PMID 38831933, 2024). "Moreover, we have previously shown that CLDN4, as well as CLDN7, binds to integrin β1 and activates FAK in BUC in gastric cancer." (PMID 35742959, 2022). "IHC scores of CDH17, CLDN18, and CLDN7 expression levels were evaluated semi-quantitatively in TMA-mounted primary lesions (IHC score (Pr)) and lymph node metastases (IHC score (LN)) taken from 106 cases of advanced gastric cancers." (PMID 27580354, 2016). "For example, reports have shown that CLDN2, CLDN7, and CLDN9 contribute to the enhanced invasion and migration of gastric cancer (GC) cells." (PMID 39199633, 2024). "Some studies report a negative association between CLDN7 expression and clinicopathological factors such as diffuse type and lymphatic invasion, while others suggest that CLDN7 overexpression promotes proliferation and EMT-driven invasion in gastric cancer cells." (PMID 40687428, 2025). "Although TROP2, CLDN7, and CEACAM5 were completely negative in adjacent normal regions, more than one-half of the regions of incomplete intestinal metaplasia, dysplasia, and gastric cancer expressed TROP2 (71.4%, 54.5%, and 53.8%, respectively) and/or CLDN7 (85.7%, 63.6%, and 63.6%, respectively)." (PMID 37196797, 2023).
colon carcinoma (19 papers, 2010 to 2025). "In Hahn-Strömberg V’s study, they found that CLDN1 rs9869263 genotype was related to risk of colon cancer and polymorphisms in CLDN7 were associated with differentiation and age of colon cancer." (PMID 30910845, 2019). "In a few instances, including expression of claudin 7 in CMS3 colon cancers and expression of occludin in CMS1 and CMS3 colon cancers, upregulation was observed in APC-mutated cases, implying a central role of the WNT/β-catenin cascade in these cases." (PMID 37998722, 2023). "We have previously demonstrated that claudin-1 mediates its pro-carcinogenic and metastatic effects through the activation of Src and Akt signaling, and claudin-7 regulates ERK signaling to modulate EMT in colon cancer." (PMID 34571860, 2021). "Consistent with this, claudin-7 was downregulated in colon cancer patient samples as compared to normal tissue." (PMID 31861759, 2019). "In contrast to claudin-1, claudin-7 has an inverse role on EMT, wherein it causes mesenchymal to epithelial transformation (MET) in Rab25 dependent manner to combat colon cancer." (PMID 31861759, 2019). "In the present study we found a correlation between the claudin-7 mRNA level, as determined by real-time RT-PCR, and the claudin-7 protein level, as determined by immunohistochemistry in normal mucosa, adenomas and carcinomas of the colon." (PMID 21310043, 2011). "In this study we relate the expression of the tight junction proteins claudin 1 and claudin 7 and the nucleotide sequence of their genes to the complexity of the invasive border of colon carcinoma." (PMID 23675182, 2010). "An aberrant expression of tight junction proteins claudin 1 and claudin 7 in colon carcinoma compared to normal mucosa was found in this study." (PMID 23675182, 2010). "CLDN7 is a well-documented tumor suppressor in colon cancer." (PMID 40687428, 2025). "To test whether PIK3CA, SLC6A6, TMEM-43, and ASAP-1 expression is driven by CLDN1 and CLDN7 expression, we analyzed these genes and proteins in CLDN1-overexpressing SW480 (SW480CLDN1) and CLDN7-knockdown DLD-1 (DLDCLDN7KD) colon cancer cell lines." (PMID 34571860, 2021). "At the same time, claudin-7 is reported to be involved in establishing MET in colon cancer." (PMID 31861759, 2019). "Similarly, others showed that elevated expression of EpCAM and altered expression of claudins, especially increases in the expression of claudin-1, −3, −4 and downregulation of claudin-7, are closely related to the metastasis process in colon cancer cells." (PMID 30289336, 2019). "Thus, a positive association between EpCAM and claudin-7 was observed in our study, which is consistent with the direct interaction between EpCAM and claudin-7 demonstrated in the previous studies in colon cancer." (PMID 24727741, 2014). "Interestingly, a recent study reported that overexpression of CLDN7 in colon cancer induced epithelial features and suppressed EMT through upregulation of Rab25 then decreased expression of p-Src and mitogen-activated protein kinase–extracellular signal–regulated kinase 1/2." (PMID 30428910, 2018). "Proteomic analysis of EVs isolated from colon carcinoma cell‐derived organoids even revealed a distinct population of exosomes according to EpCAM expression and showed a colocalization of EpCAM with CD44 and claudin 7, proteins that are known to promote tumour progression." (PMID 33343836, 2020). "CMS4 was characterized by suppression of claudin 2, claudin 3, claudin 7, and occludin and upregulation of claudin 5 mRNAs, not aligning with any of the three TCGA genomic groups or with CMS2 despite the similarities in the prevalence of common colon cancer mutations." (PMID 37998722, 2023).
esophageal squamous cell carcinoma (8 papers, 2010 to 2024). Esophageal squamous cell carcinoma (ESCC) is a type of esophageal carcinoma (EC) that can affect any part of the esophagus, but is usually located in the upper or middle third. "CLDN5 is also identified as an aberrant methylation target in pancreatic carcinoma, as well as CLDN6 in breast and esophageal squamous cell carcinoma, and CLDN7 in breast ductal and colorectal carcinoma." (PMID 36672179, 2023). "Beside proteases, CLDN7 expression was described to regulate E-cadherin expression and invasion in esophageal squamous cell carcinoma cells." (PMID 36672179, 2023). "In esophageal squamous cell carcinoma claudin-7 has been shown to enhance cell growth and metastasis." (PMID 30728783, 2018). "Though claudin-7 contributes toward cell growth and metastasis of esophageal squamous cell carcinoma, in lung cancer it inhibits migration and invasion via ERK/MAPK signaling pathway." (PMID 30728783, 2018). "CLDN7 is an integral membrane protein that has been observed to be differentially expressed in ovarian and esophageal squamous cell carcinoma cells." (PMID 25351113, 2015). "In esophageal squamous cell carcinoma cells, over-expression of claudin-7 resulted in more adhesive and less invasive cells, whereas knockdown of claudin-7 using a small interfering RNA approach led to enhanced invasion into a three-dimensional matrix." (PMID 21310043, 2011). "Study by Lioni in in vitro knockdown of claudin-7 resulted in increased invasion in esophageal SCC." (PMID 27398181, 2016). "Claudin 7 expression was found to be down-regulated in ductal carcinoma of the breast cancer, cervical cancer compared with CIN/CIS lesions, and squamous cell carcinoma of esophagus." (PMID 27398181, 2016).
pancreatic cancer (7 papers, 2007 to 2026). "Authors conclude that CLDN7 is expressed in the rapidly proliferating and dominant cell population of pancreatic cancer tissues and represents a potential molecular target for pancreatic cancer treatment." (PMID 41399659, 2026). "DNA microarray analysis showed that claudin-7 was highly expressed in MIA PaCa-2-A cells, and claudin-7 knockdown in MIA-PaCa-2-A cells significantly inhibited pancreatic tumor proliferation, reduced expression of p-Erk1/2, and inhibited G1 cell cycle arrest." (PMID 36959784, 2023). "In HEK293 and rat pancreatic cancer cell lines, EpCAM and claudin-7 were shown to form a complex which promoted migration and tumor growth, and this was associated with increased ERK signaling." (PMID 34209658, 2021).
prostate carcinoma (7 papers, 2013 to 2025). A carcinoma that arises from epithelial cells of the prostate gland. "The 7 AJ and TJ proteins chosen were E-cadherin, α- and β- catenin, ZO-1, occludin, claudin 1 and claudin 7 and their expression was investigated using an in vitro model of prostate cancer progression." (PMID 24358122, 2013). "In combination with Claudin 7, α -catenin levels in non-invasive prostate cancer cells were similar to levels in prostate epithelial cells, but like Claudin 7, was significantly decreased in the most aggressive metastatic cells." (PMID 24358122, 2013). "Claudin 7 mRNA and protein levels in non-invasive prostate cancer cells (CAHPV-10) were similar to those found in prostate epithelial cells." (PMID 24358122, 2013). "Gene combinations of OBSCN, FAM83H, CLDN7 and ARFGAP3 significantly predicted the risk of re-occurrence after treatment, demonstrating that the genes identified through this screen can have high predictive value in patients and thus are potential prostate cancer biomarkers." (PMID 27792127, 2016). "However, our in vitro investigation has shown, that out of these 7 only 3 (Claudin 7, α-catenin and β-catenin) may collectively be used to distinguish localised prostate cancer from cells representing aggressive metastatic disease." (PMID 24358122, 2013). "Therefore, Claudin 7 protein levels may be a reflection of the aggressiveness of these prostate cancer cells and may only be altered in the most aggressive form of the disease." (PMID 24358122, 2013). "The expression levels of CAV1, PALLD, ITGB8, and CLDN7 were analyzed using RT-qPCR in the normal prostate epithelial cell line RWPE1 and four prostate cancer cell lines: LNCaP, 22RV1, DU145, and PC3." (PMID 40002724, 2025). "In prostate cancer cell lines, CAV1, PALLD, and ITGB8 are upregulated, while CLDN7 is downregulated." (PMID 40002724, 2025).
endometrial cancer (6 papers, 2012 to 2025). Primary or metastatic malignant neoplasm involving the endometrium (mucous membrane that lines the endometrial cavity). "Researchers demonstrated that claudin-7 plays an important role in endometrial cancer; reduction of the expression of claudin-7 caused increased cell proliferation and invasiveness." (PMID 32197343, 2020). "Interestingly, a recent TCGA-based analysis found that low CLDN7 mRNA was enriched in high-mutational-burden endometrial cancers and linked to worse survival in certain patient subsets." (PMID 40687428, 2025). "In in vitro experiments, endometrial cancer cells with low CLDN7 were more proliferative and invasive." (PMID 40687428, 2025). "Additionaly, restoration of claudin-7 inhibited the proliferation and invasion of endometrial cancer cells, thus providing a potential therapeutic strategy." (PMID 23946785, 2013). "A low expression of claudin-7 in the endometrial cancer cells was indicative of a late tumor stage and low histological grade." (PMID 23946785, 2013). "The present study aimed to investigate the expression and function of claudin-7 in endometrial cancer." (PMID 23946785, 2013). "Claudin-7 was either overexpressed in AN3CA endometrial cancer cells, via plasmid cDNA transfection, or silenced by RNA interference in Ishikawa cells." (PMID 23946785, 2013). "In total, 31 pairs of endometrial cancer samples and their adjacent normal tissues were used to detect the expression of claudin-7 by immunohistochemical staining." (PMID 23946785, 2013). "The purpose of this study is to determine the protein expression of MSN and CLDN7 in endometrial cancer (EC) and to evaluate their prognostic value." (PMID 22272721, 2012). "Using immunohistochemical stains, our work is the first to comprehensively study the protein expression of MSN and CLDN7 in correlation with the clinical characteristics in a large series of patients with endometrial cancer." (PMID 22272721, 2012). "The first objective of our study was to explore the MSN and CLDN7 protein expression in a large series of human endometrial cancers." (PMID 22272721, 2012). "Compared with the corresponding normal tissues, 45.2% of the endometrial cancer tissues exhibited weak or absent claudin-7 protein expression." (PMID 23946785, 2013).
lymph node metastasis (6 papers, 2013 to 2025). "In salivary adenoid cystic carcinoma (SACC), the expression of CLDN7 is decreased and significantly associated with lymph node metastasis, recurrence, and gender." (PMID 40687428, 2025). "In contrast, the reduced expression of claudin-7 in oral OSCC significantly correlates with lymph node metastasis (p = 0.004) and an advanced UICC stage (p = 0.008)." (PMID 36232536, 2022). "Univariate analysis indicated that tumor topography, lymph node metastasis, and distant metastasis as well as the low expression of CLDN7 (HR = 0.97, 95% CI (0.932–0.990)) were independent risk factors for the overall survival in the patients with ChRCC." (PMID 31998788, 2020). "Claudin-4 high/claudin-1 low, claudin-4 high/claudin-7 low, and claudin-4 high/claudin-1 low/claudin-7 low types were also significantly correlated with lymph node metastasis, and showed worse survival." (PMID 31861759, 2019). "Decreased claudin-7 expression is also correlated with unfavorable prognostic factors, including invasion and lymph node metastasis, whereas patients with positive claudin-7 expression show a significantly favorable prognosis in oral squamous cell carcinoma." (PMID 24009024, 2013). "In addition, the association between reduced expression of claudin-7 in OSCC and the presence of lymph node metastases should be considered for decisions concerning lymph node dissection." (PMID 36232536, 2022). "Overexpression of CLDN7 is closely related to lymph node metastasis." (PMID 35237298, 2021). "Comparison of the expression of claudin-7 at the invasive front of the esophageal cancer with that in the corresponding metastastic lymph nodes showed significantly reduced claudin-7 expression in metastastic lymph nodes, indicating that claudin-7 may be a predictor of lymph node metastasis." (PMID 24009024, 2013). "However, multivariate analysis adjusted by age, gender, clinical stage, topography, lymph node, and distant metastasis indicated that CLDN7 no longer achieved statistical significance, but distant metastasis and lymph nodes metastasis remained statistical significance." (PMID 31998788, 2020).
invasive ductal carcinomas (5 papers, 2013 to 2022). "Of the few publications on CLDN7 expression in BC, researchers have reported that positive CLDN7 expression was significantly associated with an increased risk of recurrence and nodal involvement but with lower histological grade in a small sample of invasive ductal carcinoma (IDC) tumors." (PMID 25393310, 2014). "Claudin-7 was found to be decreased in invasive ductal carcinomas, head and neck cancer and metastatic breast cancer." (PMID 23591077, 2013). "The down-regulation of CLDN7 is found in metastatic breast cancer and invasive ductal carcinomas." (PMID 29221203, 2017).
lung adenocarcinoma (5 papers, 2018 to 2025). A carcinoma that arises from the lung and is characterized by the presence of malignant glandular epithelial cells. "In various cancers, including ovarian, testicular, endocervical, liver, and lung adenocarcinoma, CLDN7 is highly expressed and activates multiple signaling pathways involved in tumor growth, migration, invasion, and chemo-resistance." (PMID 39869563, 2025). "Tissue microarray assay in human lung adenocarcinoma and lung squamous carcinoma showed that Claudin-5 was weakly stained in adjacent tissues, whereas darkly stained in tumor tissues, but Claudin-7 staining showed the opposite results." (PMID 30874545, 2019). "For lung adenocarcinoma and endometrial carcinoma, we observed a cross-cancer effect for KRAS/NRAS-mutated cases as ATM levels are decreased, and MAPK_pT202_Y204, Claudin-7, S6_pS235_S236, and MEK1_pS217_S221 are increased in both histological tumor types consistently." (PMID 30442178, 2018). "In lung adenocarcinoma, PARP1 promotes invasion, drug resistance, and metastatic spread, in part by modulating CLDN7 expression." (PMID 40687428, 2025).
nasopharyngeal carcinoma (5 papers, 2011 to 2023). A carcinoma arising from the nasopharyngeal epithelium. "Cancer initiation cells (CICs) and nasopharyngeal carcinoma metastases in gastrointestinal tumors can be detected using CLDN7 as a marker protein." (PMID 35281827, 2022). "We investigated in this study the expression of CLDNs- Claudin1 (CLDN1) and Claudin7 (CLDN7), and their relation to tumor progression in nasopharyngeal cancer (NPC)." (PMID 28055967, 2017).
squamous cell carcinoma (5 papers, 2011 to 2024). A carcinoma arising from squamous epithelial cells. "Regarding the invasion of tumor cells, reduced expression of claudin-7 at the invasive front was found to be correlated with the depth of invasion and lymphatic involvement in squamous cell carcinoma of the esophagus." (PMID 24073219, 2013). "In squamous cell carcinomas of the oesophagus, reduced expression of claudin-7 correlates with invasion and metastasis." (PMID 21310043, 2011). "However, when comparing adenocarcinoma with squamous cell carcinoma, significant differences were observed in the expression of CLDN-3, CLDN-4, and CLDN-7." (PMID 38338691, 2024).
adenoma (4 papers, 2011 to 2023). A neoplasm arising from the epithelium. "Our results show that the claudin-7 mRNA level is decreased already as an early event in colorectal carcinogenesis, probably contributing to the compromised epithelial barrier in adenomas." (PMID 21310043, 2011).